FLOT1 (flotillin 1)
Diseases named in the same sentence as FLOT1 in open-access papers (continued):
Sharing a sentence is not in itself a finding about the gene and the disease.
cancer (continued). "CD56 and FLOT1 expressed by NK-Exos can be recognized and taken up by cancer cells, leading to cytotoxic death of cancer cells." (PMID 35962862, 2022). "Flotillin-1 (Flot-1) has been shown to regulate cancer progression, but the regulatory role of post-translational modifications of Flot-1 on cancers remains elusive." (PMID 30631151, 2019). "Several studies have found that high Flotillin-1 expression was associated with shorter overall survival (OS) and disease-free survival(DFS) in various types of cancer." (PMID 28881760, 2017). "Regarding RCC, Raimondo’s membrane proteomic study suggested that FLOT1 was up-regulated in human RCC tissues compared to para-cancer kidney tissues." (PMID 24886554, 2014). "Paired HCC lesions and adjacent noncancerous tissues displayed significantly different expression levels of FLOT1, with the cancer lesions displaying obviously higher expression of FLOT1." (PMID 23840303, 2013). "Accumulating evidence shows that the overexpression of FLOT1 in various cancers contributes to proliferative and invasive behavior as well as a worse prognosis." (PMID 24330780, 2013). "Furthermore, the level of serum FLOT1 was significantly difference between ovarian benign and malignant tumors." (PMID 40066501, 2025). "Furthermore, our results provide a strong rationale for inhibiting FLOT1 expression as a promising strategy, particularly for radiation-based cancer therapy." (PMID 40335491, 2025). "Furthermore, we found the expression level of FLOT1 was closely associated with phosphorylation of BCAR1 at Tyr 410, which plays crucial role in migration and chemoresistance of cancer therapy." (PMID 37928269, 2023). "FLOT1 plays roles in numerous biological processes including cancer-related processions." (PMID 37928269, 2023). "More studies have shown that Flotillin-1 plays an important role in the development of malignant tumors and may act as a prognosis factor in solid carcinomas." (PMID 35990908, 2022). "Flot1 regulates the migration of many cancer cells and immune cells." (PMID 34681723, 2021). "Up-regulation of Flot-1 was reported in prostate and breast cancers, esophageal squamous cells and renal cell carcinomas, and was related to the development and progression of the cancers." (PMID 30631151, 2019). "Recently, Flotillin-1 protein has considered to be a new prognostic marker for cancers." (PMID 28881760, 2017). "All these evidences suggested that FLOT1 acted as an oncogene in the tumorigenesis in many kinds of cancers, and might be a novel therapeutic target in the treatment of malignant tumors." (PMID 28549468, 2017). "Furthermore, the present meta-analysis suggested that cancer patients with elevated level of Flotillin-1 have a significantly poorer DFS, RFS and potential worse PFS." (PMID 28881760, 2017). "Since acquisition of a migratory and invasive phenotype is necessary for cancer cell dissemination, we next examined whether FLOT1 regulated NPC cell migration and invasion." (PMID 26646322, 2016). "All of these findings suggested an oncogenic role for FLOT1 in human cancers." (PMID 24886554, 2014). "Moreover, FLOT1 has been shown to promote cancer cell migration and invasion in HNSCC cells." (PMID 40335491, 2025). "Finally, different measuring method and cut-off values were applied in those studies, which may affect the availability of Flotillin-1 as a predictive biomarker in cancer prognosis." (PMID 28881760, 2017). "Caveolin-1 and flotillin-1 are considered as markers of lipid rafts which can be regarded as sorting platforms for targeted transport of transmembrane proteins and are involved in fundamental cellular events such as signal transduction, cell adhesion, lipid/protein sorting, and human cancer." (PMID 25243186, 2014).
cancer (continued). "Interestingly, we found morphological changes from the typical spindle-like shape (mesenchymal morphology) of A549/X and H520/X cells to the cobblestone-like shape (epithelial morphology) of FLOT1 knockdown A549/X and H520/X cells, suggesting that FLOT1 may endow cancer cells with EMT properties." (PMID 37131290, 2023). "Inversely, knocking down either FLOT1 or FLOT2 almost completely blocked the enhanced aggressiveness of heat-treated HCCLM3 cells in vitro and of residual cancer after insufficient RFA in vivo." (PMID 30820716, 2019). "Four studies comprising of 761 patients have investigated the relationship between Flotillin-1 expression level and DFS in cancer patients." (PMID 28881760, 2017). "However, the role of FLOT1 in development and progression of cancer remains largely unknown." (PMID 23840303, 2013). "Additionally, the sumoylation of FLOT1 enhances EMT and cancer metastasis by inhibiting the degradation of Snail, a key transcription factor that regulates EMT-related gene expression." (PMID 40303305, 2025). "In addition, the frequency of FLOT1, FLOT2, and TSG101 proteins was higher in cancer cell-line-derived exosomes when compared to control cell-line-derived exosomes." (PMID 38529947, 2024). "Although most studies on flotillins in cancer have described an elevated flotillin-2 expression, most of them did not address flotillin-1 directly or found that flotillin-1 expression has no predictive value in terms of e.g. patient survival." (PMID 24304721, 2013). "Understanding the precise roles of FLOT1 in the pathogenesis and progression of NPC and activation of the TGF-β signaling pathway will increase our knowledge of the biological basis of cancer and may also enable the development of novel therapeutic strategies against NPC." (PMID 26646322, 2016). "Our findings also suggest that flotillin 1 may be a novel biomarker for GC.These findings will not only benefit early diagnosis of this cancer at the molecular level but also improve our understanding of the initiation and development of GC." (PMID 25948494, 2015).
infection (17 papers, 2008 to 2025). The state of being infected such as from the introduction of a foreign agent such as serum, vaccine, antigenic substance or organism. "Our analysis of the 2010 cohort indicated that a host variant in the FLOT1 gene was preferentially associated with infection with a highly transmissible and functionally distinct subclade of L2 Mtb, g2g-L2 that emerged in Peru in the 1950’s." (PMID 39613754, 2024). "The researchers discovered a single host variant (located in a non-coding region of the FLOT1 gene) that was associated with infection by a particular M.tb strain they called g2g-L2." (PMID 39530100, 2024). "The host genetic variant (rs3130660) associated with g2g-L2 infection is intronic to the FLOT1 gene." (PMID 39613754, 2024). "We initially immunolocalized endogenous flotillin-1 during cultured cell infections and found it concentrated as puncta at sites of cell-to-cell spreading." (PMID 40857412, 2025). "Here, we found GFP–flotillin-1 localized along the entire length of the invaginations in the receiving cells of the infections (B’)." (PMID 40857412, 2025). "The Flot1 knock-out roots displayed a similar reduction in infection events and larger IF, as observed in the flot mutant." (PMID 38670968, 2024). "The authors posited that FLOT1-AT donors mount a robust transcriptional response to infection, potentially due to increased sensitivity in inducing innate responses." (PMID 39530100, 2024). "Using an expanded Mtb strains set, we found FLOT1 expression was significantly lower in the setting of g2g-L2 compared to non-g2g-L2 infection (two-way ANOVA, P-values = 0.0650, 0.0089, 0.0022 across three donors)." (PMID 39613754, 2024). "Our study shows that RinRK1 and Flot1 play a crucial role in NF receptor complex assembly within localized plasma membrane signaling centers to promote symbiotic infection." (PMID 38670968, 2024). "A densitometric quantification analysis of flotillin-1 confirmed the reorganization of lipid raft architecture and lipid raft perturbation by the drug upon infection." (PMID 36146865, 2022). "The cholesterol-sequestering agent methyl-β-cyclodextrin abrogated FLOT1 localization to Anaplasma inclusions and cleared infection." (PMID 30914515, 2019). "The upregulation of FLOT1 was dependent on bacterial protein synthesis because treatment with the antibiotic oxytetracycline at 1 day postinfection (dpi) completely abolished the infection and upregulation of FLOT1 at 2 dpi." (PMID 30914515, 2019). "Flotillin-1 has been implicated to be involved in a variety of different cellular processes, including endocytosis, signal transduction, regulation of cortical cytoskeleton, nerve cell regeneration and cell proliferation; and may play a role during pathogenic infection." (PMID 26186350, 2015). "Quantification of this association determined that at early time points during infection, ∼60% of the CCVs colocalized with both caveolin-1-GFP and flotillin-1-GFP." (PMID 18225954, 2008). "When we performed cell-to-cell spreading assays in Jeg3 cells simultaneously expressing GFP–flotillin-1 and mCherry–caveolin-1 in the receiving cells of the infection, we found that both flotillin-1 and caveolin-1 localized at the invaginations during these endocytic events." (PMID 40857412, 2025). "To determine whether Flot1 present in PM nanodomains, we expressed Flot1-eGFP in N. benthamiana leaves, using a construct previously demonstrated to rescue the flot infection phenotype." (PMID 38670968, 2024). "This reduction of infection events was rescued when the flot roots were transformed with Flot1." (PMID 38670968, 2024). "Interestingly, the CIB1 staining pattern was also coherent with flotillin-1 as both the molecules were more clustered with infection, compared to a diffused pattern in the uninfected HMVEC-d cells." (PMID 24550731, 2014).
infection (continued). "During infection, extracellular “microvesicles” (EMVs) are released that contain viral particles, LC3, and exosome marker FLOT1 (flotillin 1), suggesting they originated from secretory autophagy." (PMID 39394962, 2025). "Quantitative analysis of protein levels performed by dot blot scanning showed that the expression levels of ACE-2, annexin-V, flotillin-1, TLR-7, LAMP, TNF-α, caspase-1, caspase-8, and others were altered in EVs after infection." (PMID 36979955, 2023). "In the present study, we demonstrated that Anaplasma infection upregulated mRNA and protein amounts of FLOT1 in human leukocytes (HL-60 cells), and FLOT knockdown effectively blocks infection by the intracellular bacterium A. phagocytophilum." (PMID 30914515, 2019). "Also depletion of other proteins involved in caveolae-mediated endocytosis, including caveolin 1 (CAV1) and flotillins 1 and 2 (FLOT1 and FLOT2) did not affect MHV infection or fusion." (PMID 25375324, 2014).
neurodegenerative disease (3 papers, 2022 to 2025). A disorder of the central nervous system characterized by gradual and progressive loss of neural tissue and neurologic function. "The observed correlation between the abundances of flotillin 1 and p-Tau217 may reflect this paradigm, suggesting that lipid rafts may be a target for potential therapeutic interventions in HAND, as had been proposed for other neurodegenerative diseases." (PMID 34843091, 2022).
bacterial infection (2 papers, 2015 to 2019). "As with the other reported flotillin-1, SpFLT-1 expression in tissues and its localization in cells showed its potential role related to endocytosis of the tested bacterium V. alginolyticus, suggesting that SpFLT-1 may act as a key protein during the process of bacterial infection." (PMID 26186350, 2015). "FLOT1 is involved in several other intracellular bacterial infections, as FLOT1, but not FLOT2, localizes to C. pneumoniae inclusion membranes, and FLOT1 is important for C. pneumoniae intracellular growth, as determined by FLOT1 siRNA knockdown." (PMID 30914515, 2019).
kidney (2 papers, 2018 to 2022). "A substitution in an intron in the polycystic kidney and hepatic disease 1 (PKHD1) gene (rs41641297) and a SNP (rs110742604) positioned in regulatory regions of TUBB5 and FLOT1 genes." (PMID 29439661, 2018).
psychiatric disorder (2 papers, 2019 to 2020). A disorder characterized by behavioral and/or psychological abnormalities, often accompanied by physical symptoms. "Four eGenes (i.e., AS3MT, FLOT1, HLA-A, and PBRM1) are affected by eQTLs from all tested phenotypes and are current therapeutic targets for psychiatric disorders." (PMID 33192679, 2020).
adenocarcinoma (1 paper, 2014). A common cancer characterized by the presence of malignant glandular cells. "Here we present novel data on mRNA and protein expression of stomatin, flotillin-1 and −2 in human adenocarcinoma and squamous cell lung carcinoma specimens." (PMID 24533441, 2014).
benign tumors (1 paper, 2025). "Serum FLOT1 was significantly increased in patients with OC compared with healthy control (p < 0.01) and patients with benign tumors (p < 0.05)." (PMID 40066501, 2025). "To improve diagnostic sensitivity and accuracy, we evaluated the serum level of FLOT1 in OC patients and found that the serum concentration of FLOT1 as well as CA125 was significantly increased in patients with OC compared with healthy control (p < 0.01) and those with benign tumors (p < 0.05)." (PMID 40066501, 2025).
cardiovascular disease (1 paper, 2025). "Given that SLE is associated with a markedly elevated risk of cardiovascular morbidity and thrombotic events, the prominent involvement of FLOT1 in platelet coagulation pathways underscores the importance of elucidating its role in SLE-related cardiovascular disease and thrombosis." (PMID 40599891, 2025).
digestive system cancer (1 paper, 2017). A primary or metastatic malignant neoplasm involving any part of the digestive system. "The subgroup analysesshowed that the negative effect of elevated Flotillin-1 on OS was revealed in patients with RCC, LC and digestive system cancers." (PMID 28881760, 2017). "The negative effect of elevated Flotillin-1 on OS was revealed in patients with RCC (HR=2.12; 95%CI: 1.45-2.79, p<0.001) and LC (HR=1.61; 95%CI: 0.89-2.33, p<0.001), and a similar result was also observed in digestive system cancers (HR=1.47; 95%CI: 1.17-1.77, p<0.001)." (PMID 28881760, 2017).
malignant carcinomas (1 paper, 2022). "Flotillin-1 is a lipid raft-associated scaffolding protein and plays an important role in the progression and development of several malignant carcinomas." (PMID 35990908, 2022). "In addition, Flotillin-1 plays an important role in the progression and development of several malignant carcinomas." (PMID 35990908, 2022).
neurodevelopmental disorder (1 paper, 2023). A behavioral and cognitive disorder with onset during the developmental period that involves impaired or aberrant development of intellectual, motor, or social functions. "Recently, enhancement in the formation of glutamatergic synapses but not gamma-aminobutyric acid-dependent (GABAergic) synapses has been observed by modulation of Flot-1 level, which suggests further exploration of Flot-1 effect in neurodevelopmental disorders." (PMID 38067638, 2023). "In brain, anatomical and physiological studies have shown that Flot-1 enhances the formation of glutamatergic synapses but not GABAergic synapses, and it has been suggested that this protein might have a role in neurodevelopmental disorders and axon regeneration and growth." (PMID 38067638, 2023).
FLOT1 also shares sentences with these, for which no sentence is quoted: bladder transitional cell carcinoma (3 papers); nasopharyngeal carcinoma (3); neurological disorders (3); oral squamous cell carcinoma (3); acute disseminated encephalomyelitis (1); acute myelogenous leukemia (1); Anxiety (1); chronic lymphocytic leukemia (1); Cognitive impairment (1); colorectal tumor (1); cutaneous melanoma (1); endocrine disorder (1); Ewing sarcoma (1); head and neck squamous cell carcinoma (1); Hepatitis (1); Hypertension (1); invasive ductal carcinomas (1); kidney disease (1); liver cancer (1); liver cirrhosis (1); mesenchymal tumors (1); neurogenic muscle atrophy (1); optic neuritis (1); relapsing-remitting MS (1); rheumatoid arthritis (1); soft tissue sarcoma (1); thoracic cancer (1); type 1 diabetes mellitus (1); viral infection (1).